EGFR (epidermal growth factor receptor)
Diseases named in the same sentence as EGFR in open-access papers (continued):
Sharing a sentence is not in itself a finding about the gene and the disease.
tumor (continued). "Surgical specimens of patients treated with transhiatal esophagectomy were evaluated to establish EGFR expression and tumor differentiation." (PMID 22792097, 2012). "In tumor cells, cytoplasmic EGFR expression was very heterogeneous showing a small proportion of positive cells with weak intensity." (PMID 22475688, 2012). "Some studies have shown the prognostic and predictive utility of markers such as c- erb-B2 and EGFR, which influence cell growth and proliferation, in many types of tumor." (PMID 23162604, 2012). "Panitumumab is a κ IgG2 mAb that binds with high specificity and affinity to the extracellular domain of the EGFR in both normal and tumour cells, whereby it prevents the binding of ligands, dimerization, autophosphorylation, and signalling." (PMID 22997602, 2012). "Tumor samples from 155 patients with stages IIIB to IV NSCLC who received EGFR-TKI therapy were analyzed for DNA methylation status of Wnt antagonist genes, including SFRP1, SFRP2, SFRP5, DKK3, WIF1, and APC, using methylation specific PCR (MSP) method." (PMID 23009178, 2012). "Over-expression of EGFR is thought to play an important role in tumour initiation and progression of RCC because up-regulation of EGFR has been associated with high grade cancers and a worse prognosis." (PMID 22937740, 2012). "Similar western blot analyses performed on serum-starved ErbB2 tumor cells showed basal phospho-EGFR, phospho-ERK1/2 and phospho-AKT levels that were abolished by AG1478 treatment." (PMID 23028720, 2012). "It was observed in xenograft tissues that the driving force (HIF-2α) for EGFR expression was active in J cells as compared to K cells, especially in tumor cells under hypoxic conditions as observed in necrotic area." (PMID 22768190, 2012). "This spatial non-uniformity, suggests that the precise location of biopsy sampling and a subsequent classification of tumours (high or low EGFr and level of differentiation) are crucial." (PMID 22920680, 2012). "EGFR over-expression is thought to play an important role in tumour initiation and progression of RCC because the up-regulation of EGFR has been associated with a high grade and a worse prognosis." (PMID 22937740, 2012). "The tumor cell model represents those tumor cells exposed to drug concentrations equivalent to the exposure of cells with normal EGFR levels." (PMID 22399130, 2012). "The characterization of the EGFR methylation status of GB seems to be a critical issue in the delineation of the prognosis of these tumours." (PMID 22264301, 2012). "We found that EGFR expression was related with older age, poor tumor differentiation, higher pTNM staging, and shorter survival in comparison with EGFR negative cases." (PMID 22792097, 2012). "Evaluation of EGFR by immunohistochemistry as a screening method on paraffin embedded tumor tissues has been widely used recently, primarily to select patients for targeted therapies." (PMID 22475688, 2012). "There appears to be a selective pressure to lose PTEN and gain EGFR expression levels during tumor evolution." (PMID 23319880, 2012). "This shows that even in this pancreatic low EGFR-expressing cell line, the combination is more effective in inhibiting tumor cell proliferation as compared with the drugs alone." (PMID 23342262, 2012). "The radiation response of A431 tumor xenografts was enhanced with EGFR monoclonal antibody therapy and this response was noted to be maintained with continued antibody treatment after radiation." (PMID 23150825, 2012). "Considerable discrepancies were associated with histological differentiation in a way that highly differentiated tumor cells showed increased levels of EGFR in comparison with less-differentiated tumor cells." (PMID 23133538, 2012). "In support of this, EGFR expression inversely relates to responsiveness of the tumor to differentiation stimulants." (PMID 23226159, 2012).
tumor (continued). "Next, we examined EGFR expression in the tumor cells and the effect of erlotinib on the phosphorylation of EGFR, as well as its major downstream signal molecules such as Akt, ERK, Stat3, by Western blotting." (PMID 22209766, 2012). "Our simulations demonstrated that entire tumor growth profile is a collective behaviour of cells regulated by the EGFR signaling pathway and the cell cycle." (PMID 22935054, 2012). "Decorin, a member of the small leucine-rich proteoglycan gene family, exists and functions wholly within the tumor microenvironment to suppress tumorigenesis by directly targeting and antagonizing multiple receptor tyrosine kinases, such as the EGFR and Met." (PMID 23029096, 2012). "In summary, ours results demonstrate, for the first time, that Nimotuzumab enhanced the anti-tumor efficacy of radiation in EGFR high-expression ESCC cells both in vitro and in vivo." (PMID 23232108, 2012). "Concurrently, there is a marked downward trend of the phosphorylated transforming growth factor-α (TGFα)-EGFR complex in the tumor cell cytomembranes, which indicates restriction of tumor growth after CTL immunotherapy." (PMID 22394427, 2012). "There is substantial evidence that high expression of EGFR is correlated with advanced tumor stages, metastases, and poor clinical outcomes." (PMID 22322523, 2012). "High percentage of saturation of EGFR in tumor tissue was maximally achieved at the loading dose of 400 mg/m2 followed by a maintenance dose of 250 mg/m2." (PMID 22778735, 2012). "As overexpression of EGFR and ErbB2 receptors is often found in several human tumours such as breast, lung, head, and neck, ErbB receptors have been intensely pursued as therapeutic targets." (PMID 23202898, 2012). "The epidermal growth factor receptor (EGFR) is an established target for anti-cancer treatment in different tumour types." (PMID 23234355, 2012). "Paraffin sections of tumor tissue from all cases were submitted for routine H&E stains and immunohistochemistry using EGFR, CD10 and Ki67 monoclonal antibodies." (PMID 22300665, 2012). "Membrane EGFR expression in tumor cells was heterogeneous with respect to the proportion of positive cells and staining intensity." (PMID 22475688, 2012). "Further, predictions of EGFR inhibition in tumor cells are limited to those malignant cells which are exposed to similar concentrations than normal cells, such as avascular metastases embedded in healthy tissue." (PMID 22399130, 2012). "EGFR signaling impacts many aspects of tumor biology, including proliferation, invasion, spreading, and apoptosis." (PMID 22479394, 2012). "The application of this assay to a cohort of FFPE tissues surgically resected from NSCLC patients that participated in an EGFR-targeted therapeutic trial indicates its ability to monitor EGFR levels directly in patient-derived tumor tissue." (PMID 22554165, 2012). "Decorin is a key modulator of the tumour microenvironment through interactions with EGFR and MAPK pathways." (PMID 22363530, 2012). "The third rapidly expanding group provides predictive information if the potential target molecule of the therapy is present on the examined tumor sample e.g. hormone receptors, Her-2, epidermal growth factor receptor (EGFR)." (PMID 22809481, 2012). "Nimotuzumab was identified only selectively binds to tumor cells that express moderate to high levels of EGFR." (PMID 23232108, 2012). "The expression of GPR30 and EGFR was detected mainly in the cytoplasm, and the ERα and ERβ expression was detected mainly in the nuclei of the tumor specimens." (PMID 23163984, 2012). "The major mechanism by which ADAM17 contributes to tumor progression was proposed to involve the activation of growth factor receptors of EGFR (ErbB/HER) family." (PMID 23251384, 2012). "The 020913 GBM cell line maintains the primary tumor EGFR amplification as determined by a genomic copy number analysis." (PMID 23056179, 2012).
tumor (continued). "Similar results have been observed with vandetanib, an inhibitor of both VEGFR and EGFR, which when added to fulvestrant inhibited tumor growth in xenografts in greater degree compared with either agent alone." (PMID 24213497, 2012). "For example, human A431 squamous cancer cells can acquire resistance to monoclonal antibodies against EGFR by increasing tumor-induced angiogenesis owing to constitutive overexpression of VEGF." (PMID 23259795, 2012). "When in soluble form, decorin inhibits tumor growth by downregulating several receptor tyrosine kinases (RTKs) such as the EGFR, IGF-IR, and Met primarily by evoking caveolin-mediated internalization and degradation." (PMID 23029096, 2012). "The spindle cell component expressed vimentin (Dako), desmin (Invitrogen, Camarillo, CA) in 10% of tumour cells, and myogenin (Dako) in 10% of tumour cells indicating partial rhabdomyosarcoma-like differentiation, EGFR (Invitrogen), and CD56 (Invitrogen)." (PMID 23006472, 2012). "Downstream targets of EGFR form an interconnected network of phosphorylation reactions that activate transcription factors to elucidate effects including tumour proliferation, angiogenesis, and cell survival." (PMID 22997602, 2012). "As the use of EGFR and multikinase inhibitors increases, offering treatment benefits to patients diagnosed with a variety of tumor types, APs should anticipate dermatologic toxicities and treat patients in a proactive, evidence-based approach." (PMID 25031940, 2012). "The epidermal growth factor receptor (EGFR) is an important determinant of tumor response to ionizing radiation." (PMID 22681918, 2012). "EGFR TKIs are delivered through the blood vessels of tumor microvasculature and the response to treatment is studied." (PMID 22935054, 2012). "The EGFR-targeted MNT, after labeling with the residualizing [125I]SGMIB prosthetic group, bound to EGFR-expressing tumor cells with an affinity comparable to that of native EGF." (PMID 23107475, 2012). "Results demonstrate various quantitative levels of the EGFR peptide in patient tumor tissue samples with a broad range from ND to 660.73amol/μg (10X LOQ) with variation ranging from CV = 0.77 % to 35.38 %." (PMID 22554165, 2012). "Increased expression of the EGFr can lead to enhanced proliferation which can be countervailed by reducing the time available for tumour cell proliferation, thereby reducing the overall treatment time." (PMID 22920680, 2012). "Analysis of EGFR at the protein level, however, in clinical tissue samples (with respect to patient tumor profiling and targeted therapy) is typically done by immunohistochemistry (IHC) that is only subjectively quantitative through a narrow dynamic range." (PMID 22554165, 2012). "EGFR activation induces cell cycle progression, inhibition of apoptosis and angiogenesis, promotion of invasion/metastasis, and other tumour promoting activities." (PMID 22937740, 2012). "Some of these methods are so sensitive as to be able to detect even one epidermal growth factor receptor mutant tumor cell among up to 1000–2000 normal cells." (PMID 23232076, 2012). "It has been shown that GEP100 interacts specifically with EGFR and plays a pivotal role in promoting tumor invasion both in vitro and in vivo." (PMID 22701712, 2012). "Maximum EGFR-mediated tumor cell death rate was 8.97 h-1 and the steady-state concentration at the tumor that elicits 50% of maximum cell death rate was 0.81 μg/mL." (PMID 22830443, 2012). "Striking nuclear and cytoplasmic expression of HIF-2α and membranous EGFR were predominantly found at the hypoxic boundary in J cell derived tumor tissues." (PMID 22768190, 2012). "Tumor cells that were located next to the necrotic core of the tumor cell nests had lower quantities of EGFR." (PMID 22825751, 2012).
tumor (continued). "Immunohistochemical expression of EGFR mutant-specific antibodies (E746-A750del and L858R) was evaluated in whole sections of 89 tumours with available tissue after molecular analysis (89 out of 136, 65.4%)." (PMID 22952784, 2012). "Activation of epidermal growth factor receptor tyrosine kinase (EGFR-TK) enhances the cell signaling pathways allowing tumor growth." (PMID 22187555, 2012). "A study of immunocompromised mice with ER and EGFR expressing lung tumors demonstrated that estrogen significantly stimulated tumor growth which was inhibited by fulvestrant and gefitinib (an EGFR tyrosine kinase inhibitor)." (PMID 24213497, 2012). "Both tumor types are inhibited by specific anti-EGFR antibodies cells that are cultured in xenograft models." (PMID 22778735, 2012). "Both EGFR and KRAS mutations were present more commonly in ADC compared to SCC and other tumor types." (PMID 22528563, 2012). "STATs activate selected genes involved in oncogenesis, and EGFR is an upstream activator of several signaling pathways involved in tumor progression." (PMID 23118721, 2012). "'Tumor samples from 375 patients were sent to the central laboratory for EGFR assays by IHC, and evaluable assay results were obtained for 325 patients (87%)." (PMID 22642691, 2012). "In preclinical studies involving various cancer models, including ESCC, overexpression of EGFR has been found to contribute to epithelial cell proliferation, differentiation, and migration and had an inverse relationship to tumor radiocurability." (PMID 23232108, 2012). "They suggest that annexins are likely to differentially contribute and cooperate in fine-tuning of the activity of epidermal growth factor receptor (EGFR), thus regulate the growth of a variety of tumor cells." (PMID 23056502, 2012). "Statistical analysis using of clinical data for all patients, tumor type, EGFR, CD10 and Ki67 expression in relation to recurrence were evaluated." (PMID 22300665, 2012). "The antitumour activity of TAK-285 was evaluated in several murine models employing HER2- or EGFR-overexpressing human tumour xenografts such as BT-474, 4-1 ST and A431." (PMID 22240796, 2012). "In line with this, it was recently identified that the interaction of cetuximab with EGFR on BC tumor cells and FcγR IIIa on NK cells enhances cross-presentation of tumor antigens, such as EGFR, by DC to cytotoxic T lymphocytes." (PMID 23248625, 2012). "Genomic PTEN deletion, in particular homogenous deletion (P<0.001) predominantly occurred in tumours with increased gene copy number of EGFR (60.0%) and/or amplification of HER2 (63.6%)." (PMID 22240798, 2012). "Over-expression of EGFR is thought to play an important role in the initiation and progression of RCC because up-regulation of EGFR has been associated with high tumor grade and worse prognosis." (PMID 23202921, 2012). "Our simulations demonstrate that the entire tumor growth profile is a collective behaviour of its cells regulated by the EGFR signaling pathway and the cell cycle." (PMID 22935054, 2012). "Aberrant EGFR signaling in cancer is involved in increased tumor cell proliferation and growth rates, anchorage independent growth and metastasis formation." (PMID 23166750, 2012). "We have thus provided evidence for the crosstalk between EGFR and Met to be mediated through interactions between the tumor cell and the microenvironment in TNBCs." (PMID 22788954, 2012). "In vivo, EGFR knockdown in MDA-231 cells reduced tumor growth both in the mammary fat pad and the bone." (PMID 22276166, 2012). "It is known that the HSP-90 inhibitor-induced tumor cell radiosensitization is closely related to the EGFR status (reviewed by Camphausen and Tofilon,)." (PMID 22229096, 2012). "Decreased EGFR expression in the MDA-231 resulted in slower tumor growth in both the bone and the mammary gland." (PMID 22276166, 2012).
tumor (continued). "Preliminary immunohistochemical analysis discovered that more than 32% of the patients with esophagogastric junction carcinoma presented EGFR overexpression, which related with tumor stage, lymph node metastasis and postoperative tumor-free survival." (PMID 22252115, 2012). "The Lewis y antigen further promotes tumor cell proliferation by regulating the expression and phosphorylation status of molecules in the EGFR/PI3K signal transduction pathways." (PMID 22138668, 2012). "Similar to the in vitro results, treatment with panitumumab resulted in an inhibition of ligand-induced pEGFR in A431 established tumor xenograft tissue as detected by immunoprecipitation and immunoblotting with anti-pTYR and anti-EGFR antibodies." (PMID 22830443, 2012). "The EGFR staining intensity was also related to the number of tumor cells with chromosome 7 polysomy (p = 0.004)." (PMID 22475688, 2012). "EGFR is over-expressed in several tumor types, including NSCLC, and it was one of the molecules that were recognized as a biomarker for the development of targeted therapies." (PMID 23232076, 2012). "In our study, 49.8% of patients with WT KRAS tumours received an anti-EGFR agent after bevacizumab treatment." (PMID 23174912, 2012). "It has been found that CD4+ T lymphocytes can promote metastasis by activating the EGFR signaling pathway in a Th2-type tumor microenvironment." (PMID 22420471, 2012). "We have excluded the possibility that ADAM17 contributes to MC38CEA tumor progression via shedding of the ligands for EGFR and ErbB4." (PMID 23251384, 2012). "Insertions at this site of the EGFR gene result in a change in the ATP-binding pocket allowing a facilitated activation of effector proteins like RAS or PI3Kinase to promote tumor cell proliferation and survival." (PMID 23088930, 2012). "On the other hand, it is reported that the tumor cells express active EGFR even after acquiring resistance to erlotinib." (PMID 22209766, 2012). "The high SUVmax was shown to have correlations with the large tumor sizes, lymph node (LN) metastasis positives, high histologic grades, ER-negative expression, PR-negative expression, EGFR-positive expression, and high Ki-67." (PMID 22741544, 2012). "Erlotinib (Tarceva®), an oral and reversible epidermal growth factor receptor (EGFR) tyrosine kinase inhibitor (TKI), causes cell growth arrest in the G1-phase and induces apoptosis in a variety of tumor cells." (PMID 22809298, 2012). "Targeting EGFR using small molecule EGFR-tyrosine kinase inhibitors (TKI) such as gefitinib or monoclonal antibodies against EGFR (cetuximab) abrogates tumour growth in the preclinical HNSCC models." (PMID 22315058, 2012). "Taken together, the activation of EGFR in parallel with altered Notch signaling plays a critical role in the tumor suppressor function of γ-secretase." (PMID 23202921, 2012). "EGFR is known to be an important player in gliomagenesis and in the aggressive and therapeutic-resistant phenotype demonstrated by this tumor." (PMID 22530121, 2012). "EGFR belongs to a family (ErbB) of tyrosine kinase receptors which regulate tumor cell differentiation, survival, and proliferation." (PMID 22997576, 2012). "The MBED provides a new tool to estimate the effects of heterogeneity on tumour radiosensitivity and to assess the dose per fraction required for increased tumour radiosensitivity due to EGFr over-expression." (PMID 22713695, 2012). "For the EGF-CSF1 paracrine loop, a blocking antibody to the CSF-1R decreased in vivo invasion in the YB strain, indicating that in vivo invasion of the YB tumor cells was still dependent upon the EGFR-CSF-1R paracrine loop interaction with macrophages." (PMID 22314082, 2012). "Cetuximab, a new molecular drug with an extracellular action site, is expected to remarkably suppress tumor cell mitosis as an anti-EGFR monoclonal antibody." (PMID 22747970, 2012).